MTOR (mechanistic target of rapamycin kinase)
Diseases named in the same sentence as MTOR in open-access papers (continued):
Sharing a sentence is not in itself a finding about the gene and the disease.
Nephropathy (37 papers, 2010 to 2026). A nonspecific term referring to disease or damage of the kidneys. "In the logistic regression analysis, both the ELISpot risk category [OR 19 (CI 1.7–2.08)] and the use of mTOR inhibitors from the start of transplantation [OR 0.02 (CI 0.01–0.46)] were significantly associated with BKPyV-nephropathy." (PMID 40872883, 2025). "Loss of BKPyV immunity at two months is associated with nephropathy, while mTOR-based immunosuppression appears protective." (PMID 40872883, 2025). "It was previously reported that the activation of RAS stimulates the mTOR pathway in HIV-associated nephropathy." (PMID 31994601, 2020). "Testing BKPyV-specific T cells by ELISpot before and 2 months after transplantation should be a reliable marker for stratifying its risk, and the use of mTOR inhibitors could protect against BKPyV-nephropathy." (PMID 40872883, 2025). "Conversely, inhibiting mTOR by rapalogs attenuated aging‐associated nephropathy." (PMID 32400101, 2020). "In a nephropathy model, mTOR inhibitors reduced the chance of cytomegalovirus infection in serologically positive kidney transplant recipients by improving T cell fitness." (PMID 37162335, 2023). "Mammalian target of rapamycin (mTOR), a serine/threonine-protein kinase, can be activated during kidney damage." (PMID 36148005, 2022). "The reduction in podocyte autophagic activity in rats with PAN-induced nephropathy was closely related to the activation of the mTOR signaling pathway." (PMID 33881140, 2021). "We also found that cMet agonistic Ab treatment can protect against IRI‐induced kidney damage by activating the PI3K/Akt/mTOR pathway, which affects apoptosis." (PMID 32239661, 2020). "Squalene activates the AKT/mTOR signaling pathway and reduces histopathological alterations in cisplatin-induced kidney damage." (PMID 31320816, 2019). "As Lieberthal and Levine demonstrated, mTOR plays an important role in mediating the process of regeneration and recovery, depending on the kidney damage extension." (PMID 24971338, 2014). "According to the Second International Consensus Guidelines on the Management of BK Polyomavirus in Kidney Transplantation there is insufficient data to evaluate the efficacy of switching to mTOR inhibitors for treating BKPyV-DNAemia or biopsy-proven BKPyV-nephropathy." (PMID 41375853, 2025). "Interestingly, our findings also demonstrated that recipients on mTOR-based regimens had less BKPyV nephropathy." (PMID 40872883, 2025). "In addition, CMS121 modulated the AMPK, MAPK, and mTOR pathways, leading to improvement in several markers of kidney damage." (PMID 37047807, 2023). "Future studies should evaluate the involvement of the mTOR pathway in pathological conditions in human podocytes and may lead to the development of novel therapies for nephropathy that involve mTOR inhibition." (PMID 37973990, 2023). "To further explore the signaling pathways which may be related to the protective effect for fat-1 transgene in kidneys with UUO nephropathy, we examined mTOR and Smad signaling pathways in kidney tissue from various groups." (PMID 28393852, 2017). "The activation of mTOR signaling returned to normal level along with the recovery of reversible kidney injury, but in irreversible obstructed nephropathy, activation of mTOR signaling kept increasing along with the progression of fibrosis." (PMID 22470459, 2012). "Another powerful therapeutic target in the development of kidney damage is the signal transducer and activator of transcription 3 (STAT3)/PIK3R1/mechanistic target of rapamycin (mTOR) axis." (PMID 41318413, 2025). "Postoperative DM;Liver mts at 21 years;Nephropathy at 32 years.Treated with SST analogues, mTOR inhibitors, dialysis." (PMID 37152923, 2023). "Accordingly, a considerable number of studies have shown the involvement of mTOR and RICTOR in nephropathies." (PMID 34638634, 2021).
Nephropathy (continued). "Long-term kidney damage may be attenuated by reduction or even withdrawal of CNI some months after OLT while maintaining adequate immunosuppression by adding inosine monophosphate dehydrogenase (IMPDH) inhibitors or mammalian target-of-rapamycin (mTOR) inhibitors." (PMID 20380712, 2010). "In contrast, Br-MSCs + EXO, EXOs, and Br-MSCs’ transplantation caused a significant (p < 0.001) downstream regulation of mir-34a, mTOR, and AKT expression, and upstream regulation in SNHG-7, AMPK, and ULK-1 expression, respectively, compared with nephropathy and CM-treated groups." (PMID 37631363, 2023). "There was significant (p < 0.001) upregulation in the mean fold change for the relative expression of mir-34a, mTOR, and AKT and downregulation in the mean fold change for the relative expression of SNHG-7, AMPK, and ULK-1 in the nephropathy and CM-treated rats compared with control ones." (PMID 37631363, 2023). "Even in the absence of nephropathy, diabetic patients from G1 showed higher levels of mTOR compared to healthy controls." (PMID 36476132, 2022). "In the current study serum mTOR was significantly elevated in diabetic patients (with and without nephropathy) compared to controls." (PMID 36476132, 2022). "pS6RP expression, a downstream target of mTOR, increases in PECs in FSGS and healthy aging in mice, in experimental injury models including adriamycin nephropathy, puromycin aminonucleoside nephropathy, and crescentic glomerulonephritis in the rat." (PMID 32597007, 2020).
stomatitis (37 papers, 2009 to 2025). Inflammation of the oral mucosa due to local or systemic factors. "Taken together, these findings are consistent with a potential mechanistic gradient, where inhibition of PI3K or mTOR more strongly predisposes to stomatitis than targeting at the level of CDK4/6 or AKT." (PMID 41155694, 2025). "Consistent with reports in the literature, everolimus demonstrated the strongest association with stomatitis, reflecting the well-recognized toxicity profile of mTOR inhibitors." (PMID 41155694, 2025). "Alpelisib, capivasertib, and everolimus disrupt the PI3K/AKT/mTOR pathway in a manner similar to inavolisib and are associated with the incidence of stomatitis." (PMID 41155694, 2025). "Stomatitis associated with mTOR inhibitors typically manifests as discrete aphthous-like ulcerations, contrasting with the broader ulcerations seen in radiation- or chemotherapy-induced mucositis." (PMID 40227621, 2025). "Risk for stomatitis-associated adverse events is included as label warnings for other chemotherapies targeting the PI3K/AKT/mTOR pathway, with mTOR-inhibitor-associated stomatitis (mIAS) being well documented in the literature." (PMID 41155694, 2025). "The term stomatitis is preferred over mucositis to differentiate mTOR-associated mucosal ulceration from mucositis induced by radiotherapy or cytotoxic chemotherapy." (PMID 40227621, 2025). "While mTOR-inhibitor-associated stomatitis is well established, less is known about its occurrence with other kinase inhibitors in real-world settings." (PMID 41155694, 2025). "Comparisons among mTOR inhibitors revealed that patients receiving ridaforolimus experienced a significantly higher frequency of grade 3–4 mTOR inhibitor-associated stomatitis (mIAS) compared to patients receiving temsirolimus and everolimus." (PMID 38584599, 2024). "Oral lesions known as mTOR-inhibitor-associated stomatitis which develops during therapy with mammalian target of rapamycin inhibitors (mTORI)." (PMID 38420005, 2024). "Several days following the initiation of everolimus therapy, the patient developed multiple mouth ulcers, which were identified as likely manifestations of stomatitis, a known adverse effect associated with mTOR inhibitors." (PMID 39727664, 2024). "Among the most common issues is the development of ulcers of the oral mucosa (mTOR-inhibitor associated stomatitis; mIAS)." (PMID 38201496, 2023). "Nonetheless, from the standpoint of stomatitis pathogenesis, the recognition that there are differences between the two complexes in their susceptibility to specific mTOR inhibitors is important." (PMID 38201496, 2023). "Among PI3K/AKT/mTOR inhibitors, both alpelisib (OR, 0.24; 95% CrI, 0.035–1.0) and burparlisib (OR, 0.27; 95% CrI, 0.052–0.96) tended to exhibit lower risk of all-grade stomatitis than everolimus." (PMID 36091147, 2022). "Theoretically, mTOR inhibitors can promote the release of keratinocyte cytokines, directly cause epithelial injury, and eventually lead to stomatitis." (PMID 34217357, 2021). "The mTOR-inhibitor-associated stomatitis (mIAS) is, indeed, smaller, relative shallow and extremely painful." (PMID 33028357, 2020). "Unlike upper respiratory tract infections and nasopharyngitis, the risk of grade 1 and 2 stomatitis seems to be increased by the administration of mTOR inhibitors." (PMID 30760308, 2019). "According to the included studies and other reports, common adverse events of mTOR inhibitors associated with TSC therapy include stomatitis, upper respiratory tract infections, and nasopharyngitis except cough, vomiting and diarrhea." (PMID 30760308, 2019). "This review addresses the state‐of‐the‐science regarding mTOR inhibitor‐associated stomatitis (mIAS), and delineates its clinical characteristics and management." (PMID 27334013, 2016).
stomatitis (continued). "It is noteworthy that previous attempts to combine mTOR inhibitors with cytotoxic agents were associated with an increased incidence of toxicity that included dose-limiting diarrhoea and stomatitis with 5-fluorouracil and thrombocytopenia with gemcitabine." (PMID 19127256, 2009). "Our data may suggest that drugs targeting the PI3K/AKT/mTOR pathway, particularly PI3K and mTOR inhibitors, are associated with a higher risk of stomatitis than downstream targets such as CDK4/6." (PMID 41155694, 2025). "Also, some medications including immunosuppressive drugs such as calcineurin and mTOR inhibitors have been associated with severe aphthous-like stomatitis." (PMID 29653566, 2018). "Stomatitis is a common adverse event associated with mTOR inhibitors." (PMID 28938684, 2017). "Theoretically, mTOR inhibitors may induce an inflammatory reaction by inducing the release of keratinocyte cytokines, directly causing epithelial injury, which results in stomatitis." (PMID 30760308, 2019). "Stomatitis, particularly aphthous-like ulcerations, frequently occurs with mechanistic target of rapamycin (mTOR) inhibitors such as everolimus." (PMID 40868155, 2025). "Although this study focused on stomatitis reports for four PI3K/mTOR/AKT pathway inhibitors individually, many targeted therapies are used in combination with chemotherapy or radiotherapy." (PMID 41155694, 2025). "Maintenance of good oral hygiene, using a buffer mixed with mTOR inhibitor, and gargling with sucralfate or topical steroids can suitably control mild stomatitis." (PMID 35246210, 2022). "Within PI3K/AKT/mTOR inhibitors, the incidence of stomatitis, nausea, anorexia, and hepatic toxicity of different agents showed significant differences." (PMID 36091147, 2022). "In the BOLERO-2 trial, indeed, the combination treatment of everolimus, an mTOR inhibitor, with examestane was limited by a high incidence of all-grade stomatitis in metastatic breast cancer women (67% of all-grade stomatitis, 33% grade 2 and 8% grade 3)." (PMID 33028357, 2020). "A very common side effect of mTOR inhibitor everolimus is stomatitis, which presents as mouth pain, difficulty swallowing, or loss of taste." (PMID 32751138, 2020). "Stomatitis, mucositis, and mouth sores have been reported in most of the clinical studies with mTOR inhibitors (temsirolimus [75%], deforolimus [78%], and everolimus [41%])." (PMID 32578154, 2020). "In a recent retrospective study, Krueger also reported that 40% of children developed stomatitis during mTOR inhibitor treatment." (PMID 30760308, 2019). "Adverse events common with mTOR inhibitors include stomatitis, upper respiratory tract infections, and increased blood cholesterol." (PMID 29701176, 2018). "The most common adverse events in pediatric patients with TSC treated with mTOR inhibitor therapy were mouth ulceration, stomatitis, convulsion and pyrexia." (PMID 25574245, 2015). "Class-specific AEs observed with mTOR inhibitors include mild-to-moderate mouth ulcers (described as either stomatitis, mucositis, or aphthouse-like), skin rash/erythema, and some metabolic abnormalities." (PMID 21837674, 2012). "The incidence of stomatitis (52%) and other AEs was higher with ridaforolimus than with placebo; these findings were consistent with safety data reported for other mTOR inhibitors." (PMID 21837674, 2012). "In this study, no obvious stomatitis was observed during autopsy, and no weight loss due to mTOR inhibitors was observed, suggesting that feeding difficulties due to stomatitis were negligible." (PMID 38734930, 2024). "Mucositis and stomatitis are the most commonly reported adverse effects of mTOR inhibitors." (PMID 38734930, 2024). "Stomatitis is the most common AE of mTOR inhibitors with an incidence of approximately 70%." (PMID 35246210, 2022). "It is important to note that pneumonia and stomatitis are known class effects of mTOR inhibitors." (PMID 35860575, 2022).
stomatitis (continued). "Stomatitis related to mTOR inhibitors (rapamycin, everolimus, sirolimus): stomatitis is the most common AE and might be severe leading to dose adjustments." (PMID 32165025, 2020). "We found that patients who received mTOR inhibitors had a higher risk of suffering stomatitis than those who did not (RR = 3.20, 95% CI = 1.49,6.86, P = 0.003)." (PMID 30760308, 2019). "Regarding safety, compared with patients who did not receive mTOR inhibitors, those who did had a higher risk of suffering stomatitis (RR = 3.20, 95% CI = 1.49,6.86, P = 0.003)." (PMID 30760308, 2019). "In contrast to the outlined acceptable toxicity findings, a prior phase I study that combined the mTOR inhibitor temsirolimus and 5-FU demonstrated dose limiting stomatitis and hematological toxicity, and in the expansion cohort, two patients died due to mucositis with bowel perforation." (PMID 25822310, 2015). "mTOR inhibitors may be related to the development of stomatitis, mucositis, and vascular ectasia through mTOR pathways." (PMID 23841849, 2013). "Stomatitis, rash, and fatigue also are known class effects of mTOR inhibitors." (PMID 21232120, 2011). "The pathogenesis of mTOR inhibitor-associated stomatitis (mIAS) has not been fully investigated." (PMID 38201496, 2023). "Stomatitis is a common adverse event that has been reported with certain targeted therapies, including drugs targeting the PI3K/AKT/mTOR pathway." (PMID 41155694, 2025). "The incidence of stomatitis and digestive disorders was different among diverse kinds of PI3K/AKT/mTOR inhibitors." (PMID 36091147, 2022). "There was an increased incidence of mouth ulceration, stomatitis, convulsion and pyrexia in pediatric patients with TSC treated with mTOR inhibitor therapy." (PMID 25574245, 2015). "The most common adverse events of mTOR inhibitors, such as stomatitis, were reported to be mild and did not seem to influence the continuation of medication prescriptions." (PMID 37786437, 2023). "Different from conventional chemotherapy mucositis (broad ulceration with pseudo membrane formations), mTOR related stomatitis manifests as discrete aphthae on non-keratinized epithelium." (PMID 32165025, 2020). "Because the subgroup analysis of BELORO-2 shows that the incidences of mTOR inhibitor class-effect AEs, such as stomatitis, rash, and noninfectious pneumonitis, were higher among Asian patients." (PMID 28938684, 2017). "A clear relationship between mTOR inhibitors and the pathogenesis of targeted therapy-related stomatitis and GAVE has not been shown." (PMID 23841849, 2013). "Not all individuals with TSC respond uniformly to mTOR inhibitors, and adverse effects, including immunosuppression and stomatitis, may impact treatment adherence." (PMID 39727664, 2024). "However, most stomatitis events were grade 1/2 and self-limiting, which did not affect the continuation of the mTOR inhibitor." (PMID 35246210, 2022).